U6 (U6 spliceosomal RNA )
Synonyms: LOC124904986
Gene: Small nuclear RNA gene on chromosome 20 (30,713,240 to 30,713,346, reverse strand). Ensembl gene ENSG00000274385.
Gene Ontology:
Molecular function: U4 snRNA binding
Biological process: formation of quadruple SL/U4/U5/U6 snRNP; spliceosomal tri-snRNP complex assembly
Cellular component: U4/U6 x U5 tri-snRNP complex; U6 snRNP
Homologues: Orthologues: chimpanzee U6 (97% identical), macaque U6 (91% identical), macaque U6 (90% identical), dog U6 (67% identical), mouse Gm54642 (62% identical), mouse Gm22279 (60% identical), rat LOC120101210 (59% identical). Paralogues in human: RNU6-1193P (95% identical), RNU6-1269P (95% identical), RNU6-368P (95% identical), RNU6-538P (95% identical), RNU6-1320P (94% identical), RNU6-599P (94% identical), U6 (94% identical), U6 (93% identical), RNU6-316P (93% identical), RNU6-55P (93% identical), RNU6-954P (92% identical), RNU6-821P (86% identical), and 1284 more.